RNU6-30P (RNA, U6 small nuclear 30, pseudogene)
Synonyms: RNU6-30
Gene: Small nuclear RNA gene on chromosome X (101,634,006 to 101,634,112, reverse strand). Ensembl gene ENSG00000207291.
Homologues: Orthologues: chimpanzee U6 (98% identical), mouse Gm26054 (97% identical). Paralogues in human: RNU6-1 (96% identical), RNU6-15P (96% identical), RNU6-2 (96% identical), RNU6-3P (96% identical), RNU6-4P (96% identical), RNU6-5P (96% identical), RNU6-6P (96% identical), RNU6-9 (96% identical), RNU6-10P (95% identical), RNU6-12P (95% identical), RNU6-13P (95% identical), RNU6-17P (95% identical), and 1287 more.